POU1F1 (POU class 1 homeobox 1)
Description:
Transcription factor involved in the specification of the lactotrope, somatotrope, and thyrotrope phenotypes in the developing anterior pituitary. Specifically binds to the consensus sequence 5'-TAAAT-3'. Activates growth hormone and prolactin genes.
Synonyms: PIT-1; GHF-1; PIT1; POU1F1a; CPHD1
Tractability: No criterion of Open Targets' tractability assessment is met for any kind of drug.
Gene: Protein-coding gene on chromosome 3 (87,259,404 to 87,276,584, reverse strand). Ensembl gene ENSG00000064835.
Subcellular location: Nucleus
Subcellular location (Human Protein Atlas): Cytosol; Nucleoplasm
Gene Ontology:
Molecular function: DNA-binding transcription factor activity; DNA-binding transcription factor activity, RNA polymerase II-specific; protein binding; RNA polymerase II-specific DNA-binding transcription factor binding; sequence-specific double-stranded DNA binding; RNA polymerase II cis-regulatory region sequence-specific DNA binding; chromatin binding; DNA binding; DNA-binding transcription activator activity, RNA polymerase II-specific; lncRNA binding; sequence-specific DNA binding
Biological process: positive regulation of transcription by RNA polymerase II; regulation of DNA-templated transcription; negative regulation of cell population proliferation; regulation of transcription by RNA polymerase II; adenohypophysis development; negative regulation of transcription by RNA polymerase II; positive regulation of DNA-templated transcription
Cellular component: cytosol; nucleus; chromatin; RNA polymerase II transcription regulator complex
Genetic constraint (gnomAD): Loss-of-function variants: 17 observed, 27.6 expected, observed/expected ratio (o/e) 0.62, 90% interval 0.42 to 0.92. The upper end of that interval is the gene's LOEUF score, 0.92, which puts it in group 3 of 6, group 1 being the genes least tolerant of losing a copy. Missense variants: 295 observed, 332.43 expected, observed/expected ratio (o/e) 0.89, 90% interval 0.81 to 0.98. Synonymous variants: 116 observed, 115 expected, observed/expected ratio (o/e) 1.01, 90% interval 0.87 to 1.18.
Homologues: Orthologues: chimpanzee POU1F1 (100% identical), macaque POU1F1 (100% identical), pig POU1F1 (97% identical), guinea pig POU1F1 (97% identical), rat Pou1f1 (96% identical), mouse Pou1f1 (96% identical), dog POU1F1 (91% identical), rabbit POU1F1 (84% identical), tropical clawed frog pou1f1 (81% identical), zebrafish pou1f1 (70% identical), Drosophila melanogaster acj6 (32% identical), Caenorhabditis elegans unc-86 (29% identical). Paralogues in human: POU3F3 (40% identical), POU3F4 (37% identical), POU2F1 (36% identical), POU3F2 (36% identical), POU3F1 (35% identical), POU2F3 (34% identical), POU2F2 (34% identical), POU4F3 (34% identical), POU4F1 (33% identical), POU5F1 (32% identical), POU4F2 (32% identical), POU5F1B (32% identical), and 5 more.
Diseases named in the same sentence as POU1F1 in open-access papers:
POU1F1 is named in the same sentence as 42 diseases in open-access papers, as found by Europe PMC text mining. Sharing a sentence is not in itself a finding about the gene and the disease. The quoted sentences say what the papers report.
hypopituitarism (20 papers, 2014 to 2025). A condition of diminution or cessation of secretion of one or more hormones from the anterior pituitary gland. "Our study identified three pathogenic or likely pathogenic variants in the POU1F1 gene associated with combined pituitary hormone deficiency in Vietnamese patients." (PMID 40141050, 2025). "Herein, we report six patients with hypopituitarism caused by pathogenic or likely pathogenic variants in the POU1F1 gene." (PMID 40141050, 2025). "This shows the importance of long-term monitoring in patients with isolated GH deficiency to detect the progression of additional pituitary hormone deficiencies, particularly in those with POU1F1 variants." (PMID 40141050, 2025). "Our patient with a POU1F1 allelic variant is now 11 years old, and he will continue to be evaluated in terms of other pituitary hormone deficiencies and the development of APH in the follow-up." (PMID 37948564, 2023). "Mutations in several transcription factors, including HESX1, PROP1 and POU1F1 cause pituitary hormone deficiency in mice and humans." (PMID 27351100, 2016). "Pathogenic variants within the gene encoding the pituitary-specific transcription factor, POU class 1 homeobox 1 (POU1F1), are associated with combined pituitary hormone deficiency (CPHD), including growth hormone, prolactin, and thyrotropin stimulating hormone deficiencies." (PMID 35456463, 2022). "Additionally, it has been reported that two mutation sites of POU1F1 may be associated with the occurrence of combined pituitary hormone deficiency." (PMID 25360166, 2014). "There are also mutations associated with multiple pituitary hormone deficiencies, such as defects in transcription factors (mutations in HESX1, SOX 2/3, LHX3/4, PROP1, POU1F1 or PIT1, IGSF1), and in the enzyme prohormone convertase (PC1)." (PMID 39458112, 2024). "To assess the potential for digenic interaction of SIX3 and POU1F1 leading to hypopituitarism, we analyzed Six3+/−; Pou1f1+/dw mice." (PMID 35951005, 2023). "We identified two children with neonatal hypopituitarism and thin pituitary stalk who were doubly heterozygous for rare, likely deleterious variants in the transcription factors SIX3 and POU1F1." (PMID 35951005, 2023). "ACTH deficiency has been described in patients with hypopituitarism caused by PROP1, POU1F1, LHX3, LHX4, and GLI2 mutations." (PMID 33140249, 2020). "Additional pituitary deficits also arise over time in monogenic hypopituitarism caused by mutations in PROP1, POU1F1, HESX1, and other developmental genes." (PMID 33140249, 2020). "PROP-1, POU1F1, and HEX1 gene mutations were present in Turkish families with combined pituitary hormone deficiency." (PMID 32283895, 2020). "A candidate gene for the hypopituitarism phenotype, named pituitary-specific positive transcription factor 1 (POU1F1, formally PIT1) was reported in 1990 based on a spontaneous dwarf mice." (PMID 31939486, 2019). "Mutation frequencies of PROP1, POU1F1 and HESX1 in patients with combined pituitary hormone deficiencies (CPHD) vary substantially between populations." (PMID 29255988, 2018). "Mutations in several genes are known to cause hypopituitarism in children, and the pituitary transcription factors HESX1, PROP1 and POU1F1 (PIT1) are among them." (PMID 27351100, 2016). "Patients carrying mutations in the POU1F1 or PROP1 genes may present with this disorder, making it necessary to differentiate child-onset hypopituitarism from pediatric hypophysitis and pituitary hyperplasia." (PMID 41465179, 2025). "Mutations in POU1F1 cause combined pituitary hormone deficiency 1 (CPHD1, MIM #613038), which presents with hypoplasia of the anterior pituitary with multiple pituitary hormone deficiencies, resulting in severe short stature, facial dysmorphism, and poor feeding during infancy." (PMID 40141050, 2025).
hypopituitarism (continued). "POU1F1 also induces differentiation of GH-, PRL-, and TSHB-producing cell lineages in the anterior pituitary and, when mutated, causes multiple pituitary hormone deficiency syndrome and hypopituitarism." (PMID 37600690, 2023). "GH gene expression is controlled, among others, by the pituitary-specific transcription factors POU class 1 homeobox 1 (POU1F1) and PROP paired-like homeobox 1 (PROP1), which are also implicated in adenohypophysis development and associated with hypopituitarism." (PMID 34680948, 2021). "Hypopituitarism can have a congenital cause due to mutations in genes involved in pituitary development and endocrine cell differentiation, such as POU class 1 homeobox 1 (POU1F1, also known as PIT1) and orthodenticle homeobox 2 (OTX2) or can be acquired during life." (PMID 37614709, 2023). "Also in 90s, inactivating mutations of the transcription factor of POU1F1 gene (PROP1) in an autosomal recessive pattern were also described in individuals with hypopituitarism, with or without gonadotropic deficiency." (PMID 31939486, 2019).
breast carcinoma (12 papers, 2013 to 2026). "Pit-1 (also known as POU1F1) is expressed in the mammary gland, and its deregulation induces a malignant phenotype in breast cancer cells associated with tumor growth and metastasis." (PMID 25992773, 2015). "Using POU1F1-overexpressing and knock-down breast cancer cell lines, as well as immunodeficient mouse models, our data demonstrate that POU1F1 induces a BCSC-like phenotype in breast tumor cells by deregulating markers such as CD24, CD44, CD133, and ALDH." (PMID 41857068, 2026). "In breast cancer, POU1F1 transcription factor in breast cancer cells enhances LDHA expression and promotes pro-lactate and secretion into the TAM." (PMID 40565047, 2025). "In pancreatic and breast cancer, the polarization and recruitment of M2 macrophages is regulated by the POU1F1/CXCL12/CXCR4 signaling axis to promote tumor metastasis." (PMID 37415241, 2023). "Conversely, LDHA knockdown in breast cancer cells that overexpress POU1F1 decreases tumor volume and [18F]FDG uptake in tumor xenografts of mice." (PMID 33714987, 2021). "A more recent study has demonstrated that POU1F1 promotes breast cancer metastasis via recruitment and polarization of macrophages into TAMs15." (PMID 33927188, 2021). "High POU1F1 levels in breast cancer cells induce cell proliferation, reduce apoptosis, and increase migration and invasion." (PMID 33714987, 2021). "In the present study, our first objective was to evaluate possible metabolic changes in breast cancer mediated by POU1F1." (PMID 33714987, 2021). "High POU1F1 expression in breast cancer cells is related to high cell proliferation, migration, invasion, and low apoptotic rate." (PMID 33714987, 2021). "Both POU1F1/LDHA and POU1F1/α-SMA expression correlate with clinical outcome, suggesting POU1F1 as a prognostic factor in breast cancer." (PMID 33714987, 2021). "Human breast cancer cell lines and primary human breast tumors were used to evaluate the effect of POU1F1 overexpression and POU1F1 knockdown in the glycolysis pathway." (PMID 33714987, 2021). "Given that POU1F1 is related to pituitary gland development and cancer progression, we analyzed these biological processes in the context of breast cancer." (PMID 33714987, 2021). "In recent years, several studies support a critical role for POU1F1 in breast cancer progression and metastasis." (PMID 33927188, 2021). "Hypomethylation profiles in clusters of circulating breast cancer cells have recently been identified in binding sites for several transcription factors related to stemness and proliferation, including POU1F1." (PMID 33714987, 2021). "Rsk and Plk1 both suppress DNA-damage checkpoint signaling by phosphorylating and inhibiting MRE11 activity, whilst FGFR2 regulates MRE11 expression through the MEK/ERK/POU1F1 pathway in breast cancer." (PMID 33927349, 2021). "Similar data were obtained for the human breast tumors and the breast cancer cell lines, which strongly suggests that POU1F1 regulates the glycolysis pathway in breast tumors." (PMID 33714987, 2021). "The current study demonstrates that the POU1F1 transcription factor induces metabolic reprogramming by enhancing aerobic glycolysis of human breast cancer cells through transcriptional regulation of the LDHA gene." (PMID 33714987, 2021). "In addition to the well‐known effects on growth hormone and prolactin gene transcription, it has been demonstrated that CD163+ macrophages induce POU1F1 expression in breast cancer cells." (PMID 36373483, 2023). "For instance, the transcription factor POU class 1 homeobox 1 (POU1F1, also known as Pit-1), a protein expressed by breast cancer cells, has been reported to increase macrophage recruitment and to promote their polarization towards VEGFA-expressing tumor-promoting macrophages." (PMID 35309358, 2022). "The current study analyzes the role of POU1F1 in breast cancer cell metabolism." (PMID 33714987, 2021).
breast carcinoma (continued). "Recent mechanistic study has revealed that high POU1F1 expression in breast cancer patients is positively correlated with metastasis in liver and lung, and POU1F1/CXCL12/CXCR4 axis is involved in macrophage recruitment and polarization, as well as metastatic process." (PMID 33927188, 2021). "In fact, high expression of POU1F1 in breast cancer correlates with poor clinical outcome." (PMID 33714987, 2021). "Moreover, POU1F1-induced CXCL12 in breast cancer cells promotes recruitment and polarization of macrophages into TAMs." (PMID 33096815, 2020). "This suggests an increased transcriptional activity of POU1F1 and consequently increased expression of LDHA in highly aggressive breast cancer cell lines." (PMID 33714987, 2021). "Previous studies have demonstrated that POU1F1/CXCL12/CXCR4 axis contributes to macrophage recruitment and polarization, thereby promoting breast cancer metastasis." (PMID 33927188, 2021). "POU1F1 expression has also been reported in hematopoietic and lymphoid tissues, and its expression was correlated with increased cellular proliferation in breast cancer and human myeloid leukemic cells, leading to the suggestion that POUF1 may be involved in the regulation of cellular proliferation." (PMID 23332017, 2013). "In patients, POU1F1 and LDHA mRNA expression was correlated with breast cancer clinical outcome." (PMID 33714987, 2021). "Indeed, a significant (P = 0.048, HR = 1.13 (1–1.28)) relationship between POU1F1/ACTA2 mRNA levels and RFS was found in a human breast cancer dataset (n = 3951 samples), which suggests a clinical prognostic value for both POU1F1 and α-SMA in breast tumors." (PMID 33714987, 2021). "Finally, to study the possible relationship between POU1F1/LDHA expression and clinical outcome, POU1F1 and LDHA mRNA was analyzed in a dataset of human breast cancer patients." (PMID 33714987, 2021). "In addition, POU domain class 2 transcription factor 1 (known as POU1F1 (Pit-1)) induces the expression of both CXCR4 and CXCL12 in breast cancer cells." (PMID 33096815, 2020). "Once we demonstrated that POU1F1 regulates LDHA and that pharmacological or genetic manipulation of LDHA induces phenotypic changes in breast cancer cells that modify cancer progression, we studied whether POU1F1 could have an impact on TME, specifically on fibroblasts." (PMID 33714987, 2021).
adenoma (7 papers, 2013 to 2023). A neoplasm arising from the epithelium. "The gene encoding PIP5K1B, known to participate in the regulation of cell cycle, proliferation, migration and apoptosis was significantly overexpressed in POU1F1 adenomas." (PMID 35260162, 2022). "In contrast, the expression of the different genes encoding cyclins, CDK and CDK inhibitors among NR5A1-, POU1F1- and TBX19-adenomas showed only subtle differences." (PMID 35260162, 2022). "While 81.8% of the POU1F1-derived functioning adenomas were found to be recurrent upon follow up, that was the case for only 50% of the NR5A1-derived NFPA." (PMID 33261069, 2020). "Thus, NR5A1-, POU1F1- and TBX19-derived adenomas shared the same expression level of most genes encoding the different cyclins, CDK and CDK inhibitors." (PMID 35260162, 2022). "By contrast, the expression of genes that encode cyclins and CDK and CDK inhibitors among TBX19, NR5A1, and POU1F1 adenomas is not so different." (PMID 36968144, 2023).
pituitary adenomas (6 papers, 2014 to 2024). "Consistent with the histologic differentiation, the M6 pituitary adenoma showed massive upregulation of POU1F1 and PITX1, high overexpression of PITX2 and NR4A1-3, but minimal or absent expression of TBX19 and NR5A1, respectively." (PMID 35978432, 2022). "In the present work we carried out proteomic and transcriptomic analyses to identify altered genes related to splicing events in pituitary adenomas derived from POU1F1 and NR5A1 cell lineages." (PMID 33261069, 2020). "In the current study, a significant decrease of POU1F1 was detected in the pituitary adenoma tissues." (PMID 25360166, 2014). "Therefore, we propose that the significantly decreased expression of the POU1F1 gene is a pivotal factor, leading to the reduction of pituitary hormone secretion in pituitary adenoma." (PMID 25360166, 2014). "Silent pituitary adenomas immunostain for ACTH and TBX19 (silent corticotroph adenomas), or for PRL, or GH, and POU1F1 (silent lactotroph or somatotroph adenomas, respectively)." (PMID 38612778, 2024). "The other genes including POU1F1, IGFBP3, and CCNB1 were also reported to correlate with pituitary adenomas." (PMID 25642247, 2015). "The pituitary adenomas derived from POU1F1- and NR5A1-cell lineages as well as the non-tumoral gland share a total of 1780 proteins." (PMID 33261069, 2020).
somatotroph adenomas (5 papers, 2020 to 2025). "We also compared Subtype 1 somatotroph tumors to the other acromegaly-associated tumors (combined Subtypes 2 and 3) and examined the enrichment of DEGs with NR5A1 and POU1F1 regulons." (PMID 40813692, 2025). "Intriguingly, we revealed distinct groups as follows: 1) somatotroph adenoma: high POU1F1 and high DLK1; 2) lactotroph adenoma: high POU1F1 and low DLK1; 3) gonadotroph adenoma: high FSHB and low DLK1, followed by high GATA2 and low DLK1; and 4) corticotroph adenoma: high TBX19 and low DLK1." (PMID 33472171, 2020).
gastric cancer (4 papers, 2021 to 2025). A primary or metastatic malignant neoplasm involving the stomach. "An example of a novel regulator-based PCM is a module associated with the developmental transcription factor POU1F1, whose significant activation conferred worse prognosis in stomach cancer (KM p = 9.8 × 10−4; hazard ratio = 0.3)." (PMID 36950380, 2023). "Collectively, these data suggest an oncogenic role of POU1F1 in the tumorigenesis of gastric cancer." (PMID 33927188, 2021). "Finally, the POU1F1-derived tumors showed alterations in phosphatidylinositol signaling pathways which is altered in neuroendocrine tumors, hematopoietic malignancies, breast, colon and gastric cancer." (PMID 35260162, 2022). "Furthermore, the high mobility group A 1B/2 was shown to upregulate the expression of POU class 1 homeobox 1 (POU1F1), which regulates M2-like macrophage polarization via the CXCL12/CXCR4 signaling axis, and contributes to the metastasis of gastric cancer to the lungs." (PMID 40028336, 2025).
hypophysitis (3 papers, 2021 to 2025). Inflammation of the pituitary gland. "Anti-POU1F1 hypophysitis (anti-POU1F1 antibody syndrome) is a newly described pituitary autoimmune disease characterized by acquired and specific growth hormone (GH), prolactin (PRL), and thyroid-stimulating hormone (TSH) deficiencies." (PMID 41465179, 2025).
pituitary tumor (3 papers, 2020 to 2025). A benign or malignant neoplasm affecting the pituitary gland. "Our results underscored the participation of spliceosome components in the molecular machinery of the pituitary tumors pathogenesis derived from POU1F1- and NR5A1-cell lineages and the alteration of the mRNA splicing patterns characteristic to each tumor." (PMID 33261069, 2020). "mRNA isoforms generated by alternative splicing appear to be specific for POU1F1- and NR5A1- derived pituitary tumors and could potentially be used as molecular markers as well as specific targets for molecular therapy." (PMID 33261069, 2020).